ZNF254 (zinc finger protein 254)
Description:
May be involved in transcriptional regulation.
Synonyms: BMZF-5; HD-ZNF1; ZNF539; ZNF91L
Tractability: PROTAC: ubiquitination databases record sites on it.
Gene: Protein-coding gene on chromosome 19 (24,033,405 to 24,129,968, forward strand). Ensembl gene ENSG00000213096.
Subcellular location: Nucleus
Pathways (Reactome):
Gene expression (Transcription): Generic Transcription Pathway
Gene Ontology:
Molecular function: DNA-binding transcription factor activity, RNA polymerase II-specific; RNA polymerase II cis-regulatory region sequence-specific DNA binding
Biological process: negative regulation of transcription by RNA polymerase II; regulation of transcription by RNA polymerase II; regulation of DNA-templated transcription
Cellular component: nucleus
Genetic constraint (gnomAD): Loss-of-function variants: 9 observed, 11.36 expected, observed/expected ratio (o/e) 0.79, 90% interval 0.48 to 1.38. The synonymous counts are far from expectation, so gnomAD's model fits this gene poorly and the ratio says little. Missense variants: 994 observed, 761.04 expected, observed/expected ratio (o/e) 1.31, 90% interval 1.24 to 1.38. Synonymous variants: 305 observed, 248.47 expected, observed/expected ratio (o/e) 1.23, 90% interval 1.12 to 1.35.
Homologues: Orthologues: chimpanzee ZNF254 (99% identical), macaque ZNF254 (91% identical). Paralogues in human: ZNF726 (73% identical), ZNF728 (67% identical), ZNF724 (66% identical), ZNF681 (64% identical), ZNF429 (64% identical), ZNF43 (63% identical), ZNF85 (63% identical), ZNF93 (63% identical), ZNF708 (63% identical), ZNF676 (63% identical), ZNF493 (61% identical), ZNF90 (60% identical), and 164 more.
Diseases named in the same sentence as ZNF254 in open-access papers:
ZNF254 is named in the same sentence as 2 diseases in open-access papers, as found by Europe PMC text mining. Sharing a sentence is not in itself a finding about the gene and the disease.
ZNF254 shares sentences with these, for which no sentence is quoted: cancer (1 paper); ovarian carcinoma (1).